ZNF320 (zinc finger protein 320)
Description:
May be involved in transcriptional regulation.
Synonyms: ZFPL; DKFZp686G16228
Tractability: PROTAC: ubiquitination databases record sites on it.
Gene: Protein-coding gene on chromosome 19 (52,860,851 to 52,897,704, reverse strand). Ensembl gene ENSG00000182986.
Subcellular location: Nucleus
Subcellular location (Human Protein Atlas): Nucleoplasm; Cytoplasmic bodies
Pathways (Reactome):
Gene expression (Transcription): Generic Transcription Pathway; Regulation of endogenous retroelements by KRAB-ZFP proteins
Gene Ontology:
Molecular function: protein binding; DNA-binding transcription factor activity, RNA polymerase II-specific; RNA polymerase II cis-regulatory region sequence-specific DNA binding
Biological process: regulation of transcription by RNA polymerase II; regulation of DNA-templated transcription
Cellular component: nucleus
Genetic constraint (gnomAD): Loss-of-function variants: 1 observed, 3.5 expected, observed/expected ratio (o/e) 0.29, 90% interval 0.1 to 1.31. That is too few expected variants to judge how well the gene tolerates losing a copy. Missense variants: 468 observed, 609.34 expected, observed/expected ratio (o/e) 0.77, 90% interval 0.71 to 0.83. Synonymous variants: 204 observed, 199.88 expected, observed/expected ratio (o/e) 1.02, 90% interval 0.91 to 1.15.
Homologues: Orthologues: chimpanzee ZNF320 (99% identical). Paralogues in human: ZNF600 (58% identical), ZNF611 (55% identical), ZNF534 (51% identical), ZNF28 (49% identical), ZNF528 (48% identical), ZNF836 (48% identical), ZNF841 (48% identical), ZNF595 (48% identical), ZNF708 (46% identical), ZNF33B (46% identical), ZNF726 (46% identical), ZNF728 (46% identical), and 164 more.
Diseases named in the same sentence as ZNF320 in open-access papers:
ZNF320 is named in the same sentence as 7 diseases in open-access papers, as found by Europe PMC text mining. Sharing a sentence is not in itself a finding about the gene and the disease. The quoted sentences say what the papers report.
breast carcinoma (1 paper, 2019). "For breast cancer, the number of KRAB‐ZNF‐positive samples was slightly different: (ZNF205 – 6/11, ZNF320 – 10/10, ZNF485 – 11/11, ZNF643 – 11/11, ZNF695 – 12/12, ZNF 707 – 10/10, and ZNF789 – 2/12)." (PMID 30444046, 2019).
glioblastoma (1 paper, 2015). The most malignant astrocytic tumor (WHO grade IV). "Specifically, ZNF320 has been shown to be implicated in glioblastoma." (PMID 26625115, 2015).
hepatocellular carcinoma (1 paper, 2022). A malignant tumor that arises from hepatocytes. "In our study, we figured out ZNF320 as a new potential prognostic biomarker for hepatocellular carcinoma., and studied the relationship between ZNF320 and cell cycle, tumor-associated immune cells, m6a." (PMID 36287187, 2022). "The importance and originality of this study are that it reveals the important function of ZNF320 in hepatocellular carcinoma and provides a potential link between ZNF320 and cell cycle, HCC immune invasion, m6A Modification and its underlying mechanisms." (PMID 36287187, 2022). "To further find the potential role of ZNF320 expression in TCGA patients with Hepatocellular Carcinoma, we used Kaplan Meier survival method for survival analysis." (PMID 36287187, 2022). "In conclusion, our research suggests that ZNF320 may be a possible biomarker for poor prognosis of hepatocellular carcinoma." (PMID 36287187, 2022).
liver cancer (1 paper, 2022). An epithelial or non-epithelial malignant neoplasm that arises from the liver. "It is supposed that the increased methylation level of ZNF320 promoter leads to the high ZNF320 expression in liver cancer, which in turn causes poor prognosis in patients with liver cancer." (PMID 36287187, 2022). "In conclusion, ZNF320 may be a prognostic biomarker related to immunity as a candidate for liver cancer." (PMID 36287187, 2022).
lung carcinoma (1 paper, 2019). "The smallest significant difference was noticed for ZNF205 in lung cancer (LUAD: FC = 1.4, P < 0.01; LUSC: FC = 1.3, P < 0.01; t‐test with Tukey HSD correction) and ZNF320 in BRCA (FC = 1.1, P < 0.001; t‐test with Tukey HSD correction)." (PMID 30444046, 2019). "In lung cancer tissue samples, KRAB‐ZNF staining was positive for at least four analyzed tumor samples (ZNF205 – 4/12, ZNF320 – 10/10, ZNF485 – 11/11, ZNF643 – 10/11, ZNF695 – 8/9, ZNF 707 – 10/11) and at least one sample from each set presented nuclear localization of a given factor." (PMID 30444046, 2019).
cancer (5 papers, 2019 to 2023). A tumor composed of atypical neoplastic, often pleomorphic cells that invade other tissues. "Additionally, ZNF320 were associated with patients’ cancer stages, and patients in more advanced cancer stages has a tendency to have higher expression of ZNF320." (PMID 36287187, 2022). "Our results show that the cancer-promoting impact of ZNF320 is associated with the modification of m6a, which may influent the mRNA methylation level of HCC through its association with YTHDF1, and finally impact the progress of HCC." (PMID 36287187, 2022). "These put forward that ZNF320 may serve as a target for early clinical diagnosis and treatment which may have a chance to improve diagnostic and therapeutic options, and at the same time provides a reference for further exploration of new cancer immunotherapy." (PMID 36287187, 2022). "The literature shows that some KZNFs are up-regulated in cancer, including ZNF695, ZNF320, ZNF200, ZNF354A, ZNF707, ZNF138 and so on." (PMID 37370088, 2023). "The results indicated that the functional classification and KEGG pathway related to ZNF320 included: “FC epsilon pathway”, “FC gamma R mediated phagocytosis”, “cell cycle”, “WNT signaling pathway”, “pathway in cancer”, “leukocyte transendothelial migration”, “mismatch repair” and so on." (PMID 36287187, 2022).
tumor (2 papers, 2019 to 2022). "Although ZNF320 and CD8+ T cell infiltration are associated, we found that ZNF320 is positively correlated with the immune checkpoint gene, cannot produce tumor killing benefits, and is actually involved in immune escape." (PMID 36287187, 2022). "In conclusion, our results showed that there is an association between ZNF320 and tumor cell infiltration in HCC." (PMID 36287187, 2022). "At the same time, results showed that ZNF320 has been associated with many clinicopathological parameters, including tumor grade, tumor stage, and so on." (PMID 36287187, 2022). "Our results showed that ZNF320 expression protein in HCC tissues was conspicuously higher than that of adjacent tumor tissues." (PMID 36287187, 2022). "Therefore, ZNF320 constitutes an immunosuppressive microenvironment by affecting the expression levels of relevant chemokines, helping tumor cells to participate in immune escape, thereby enhancing tumor cell invasion and migration capabilities." (PMID 36287187, 2022). "Finally, TIMER and GEPIA analysis verified that ZNF320 expression is closely related to tumor infiltrating immune cells (TIIC), including B cells, CD8+ T cells, CD4+ T cells, macrophages, neutrophils, and dendritic cells." (PMID 36287187, 2022). "In conclusion, these results proclaimed that ZNF320 was related to tumor cell infiltration in HCC." (PMID 36287187, 2022). "Through analyzing whether ZNF320 expression was associated to immune infiltration levels in HCC, we discovered a positive correlation between ZNF320 expression and tumor purity, infiltrating levels of B cells, CD8+ T cells, CD4 + T cells, Macrophage, Neutrophils, and Dendritic cell." (PMID 36287187, 2022). "Besides, we also investigated the possible mechanism of high expression of ZNF320 in HCC and the relation of ZNF320 expression and cell cycle, tumor infiltrating immune cells in HCC patients." (PMID 36287187, 2022). "ZNF320 may not only take part in cell cycle regulation and affect the proliferation of HCC, but also may assume the role in the microenvironment of HCC by regulating tumor infiltrating immune cells." (PMID 36287187, 2022).